CD68 (CD68 molecule)
Diseases named in the same sentence as CD68 in open-access papers (continued):
Sharing a sentence is not in itself a finding about the gene and the disease.
breast carcinoma (continued). "The recruitment rate was estimated by the median density of TAMs measured in tumor nests from patients with basal-like breast cancer, a subtype similar to TNBC, by immunohistochemistry using a pan-macrophage marker, CD68." (PMID 35856032, 2022). "M1 markers (CD80 and CD86) showed a better correlation with markers of endothelial activation compared with total macrophage marker (CD68) and with M2 markers (CD163 and CD206) in breast cancer samples." (PMID 36248978, 2022). "To demonstrate its clinical relevance, we assessed the correlation between PYK2 expression (PTK2B gene) and macrophage markers (CD68, CD163) in human breast cancer datasets." (PMID 35092356, 2022). "In the breast cancer tissue itself, 30% of dendritic cells, 20% of CD45 positive cells, 15% of CD11b positive cells, and 5% of CD68 positive cells were found." (PMID 33921688, 2021). "It was demonstrated that CD163 is predominantly expressed on CD14+CD68+ monocyte-derived macrophages, which infiltrate tumor mass, indicating that NAC can induce the recruitment of CD163+ monocytes into breast cancer tumor." (PMID 35237501, 2021). "In an existing cohort of early-stage breast cancer patients, CLS-B were identified using H&E stained histologic sections (hCLS-B), and by CD68 immunohistochemistry (CD68 + CLS-B)." (PMID 34294716, 2021). "We performed IHC on a TMA including 231 primary tumors from patients with metastatic breast cancer, to identify T lymphocytes (CD3+ cells), macrophages (CD68+ cells), and neutrophils (NE+ cells)." (PMID 33602289, 2021). "In metastatic brain lesions that originated from breast cancer, a higher degree of 18F-FDG uptake was observed in those with high expression of CD68." (PMID 34249674, 2021). "The IHC staining with anti-CD68, anti-CD4, and anti-CD8 detected CD68+ macrophages, CD4+, and CD8+ T cells, respectively, in rat mammary tumors." (PMID 34164110, 2021). "The CD68-positive and CD-11b-positive inflammation-related cells were immunostained in the tumors from nude mice injected with WT or QTRT1-KO breast cancer cells, indicating an immune response inside the tumors." (PMID 32182756, 2020). "Taken together, our results successfully demonstrated that the expression of the immune cell subtype-related proteins STAT6, FOXP3, CD8, CD68, and CD163 was different according to the molecular subtype of breast cancer." (PMID 32580398, 2020). "Oppositely, the analysis of TAMs in 200 cases of basal-like BC (which is similar to TNBC) showed that increased stromal infiltration of CD68+ or CD163+ macrophages correlated with higher 5-year recurrence and 5-year breast cancer mortality." (PMID 33194645, 2020). "Here, we retrospectively studied the distribution of both CD68+ and CD163+ TAMs in 1579 early stage breast cancer specimens, which currently represents the largest sample size to date." (PMID 31528210, 2019). "In this study, the expression of CD68 was positively correlated with that of CD47, and CD47highCD68high was found in 49.8% of breast cancer patients." (PMID 31528120, 2019). "In breast cancer with adipose stroma, the number of CD163-positive macrophages was greater with stromal ATX positivity (p = 0.003), and the number of CD68-positive and CD163-positive macrophages were greater in cases with stromal LPA3 positivity." (PMID 31035435, 2019). "The subtype-dependent TAMs abundance was confirmed with microarray expression data showing that the basal-like breast cancer had significantly higher levels of CD163 and CD68 mRNAs compared to luminal breast cancer." (PMID 31406165, 2019). "Two hundred seventeen cases of breast cancer tissues and 40 cases of benign breast lesions were collected for immunohistochemical staining of CD47 and CD68." (PMID 31528120, 2019).
breast carcinoma (continued). "Here, we have objectively and simultaneously measured in situ the expression of TAM biomarkers (CD68, CD163, and the druggable target MMP-9) in two distinct breast cancer cohorts by using the validated quantitative immunofluorescence (QIF) AQUA method." (PMID 30558648, 2018). "ER is amongst the most important biomarkers for breast cancer; thus, all three TAM biomarkers (CD68, CD163, and MMP-9) are examined in the context of ER status." (PMID 30558648, 2018). "Double immunostaining of human breast carcinomas of grade III for p110δ and CD68 revealed strong p110δ staining in macrophages (CD68+ cells), which had an intensity similar with that measured in cancer cells." (PMID 29880805, 2018). "Alternatively, the CD68:CD8 ratio can also be analysed through microarray analysis and this has been shown to predict survival and chemotherapeutic response in breast cancer." (PMID 26943587, 2016). "Excessive production of CCL18 in tumor-infiltrating macrophages was demonstrated in gastric cancer, breast cancer, colorectal cancer, and cutaneous T-cell lymphoma via CCL18 and CD68 co-immunostaining." (PMID 26919103, 2016). "To explore the clinical relevance of TAM differentiation in breast cancer patients, we evaluated total TAM number (CD68), M1 TAM (HLA-DRα) and M2 TAM (CD163) in a large human breast cancer TMA cohort." (PMID 26243145, 2015). "Previously, we reported that CCL18 is a major cytokine released by TAMs and enhances breast cancer cell metastasis; moreover, CCL18 and CD68 colocalization in breast cancer tissues confirmed that CCL18-immunopositive cells represent a subset of macrophages." (PMID 26416449, 2015). "In breast cancer, the tumor stroma was infiltrated by CD163+ and CD68+ macrophages, CD163+ macrophages positively correlated with higher grade and larger tumor size, and CD68+ macrophages positively correlated with tumor size." (PMID 24883329, 2014). "Our choice of an open-source software analysis of digital images for quantifying breast cancer TIL and CD68 was also undertaken to avoid inter-observer bias and to favor the future standardization of TIL evaluation." (PMID 25432519, 2014). "In this work, we show that the pre-treatment profile of immune cell subpopulations is able to identify a highly responsive group of breast carcinomas characterized by a high CD4, CD68 and CD20 and a low CD8 infiltration." (PMID 25432519, 2014). "One hundred and two breast cancer cases from I-SPY 1 were stained with anti-PCNA and anti-CD68 antibodies and the double positive PCNA+ TAMs enumerated." (PMID 24205370, 2013). "Triple-negative/basal-like and luminal A breast cancers had different recruitment or differentiation patterns of CD163+ and CD68+ macrophages in TS." (PMID 22824040, 2012). "Eighty percent of the triple-negative/basal-like breast cancer patient had dense infiltration of CD163+ macrophages in TS, while 23% had dense infiltration of CD68+ macrophages in TS." (PMID 22824040, 2012). "Therefore, the aim of this study was to analyze whether CD163 can be used as a marker for TAMs and to compare its prognostic value with the more frequently used pan-macrophage marker CD68 in a tissue microarray (TMA) with tumors from 144 breast cancer patients." (PMID 22824040, 2012). "Some studies have shown that the five-year progression-free survival (PFS) is higher in non-metastatic breast cancer patients with low expression of CD68-positive macrophages and that the prognosis of patients is worse when CD68 positivity is highly expressed." (PMID 41256322, 2025). "In this context, breast cancer progression from ductal carcinoma in situ (DCIS) to invasive ductal carcinoma (IDC) was accompanied by a gradual increase in immune infiltration, particularly involving CD8+ T cells and CD68+ macrophages." (PMID 41018083, 2025).
breast carcinoma (continued). "Then, the distribution of TAMs was investigated in tissues of breast cancer and paracarcinoma; we found that the expression level of PGRN was proportional to the expression level of CD68 and CD68+ macrophages were accumulated within and around the tumor tissues." (PMID 38554213, 2024). "To our knowledge, we are the first who compared CD68, CD163, CSF-1R and CD206 for TAM detection and assessed their relation with clinicopathological characteristics in a large well-characterized series of intrinsic breast cancer subtypes." (PMID 36622544, 2023). "Similar findings were demonstrated by Egeblad and colleagues in breast cancer, showing that non-migratory macrophages present within the tumor body were mostly CD68+ CD206neg." (PMID 37958292, 2023). "In the largest study to date, we recently investigated this topic in a diverse cohort of Black and White breast cancer patients unrestricted to outcome and used CD68 to identify CLS-B in non-tumor-containing breast adipose tissue." (PMID 34066392, 2021). "Specific role of CD204 was found in the Japanese cohort, where high number of CD204+ but not CD68+ or CD163+TAMs was associated with worse relapse-free survival and breast cancer-specific survival." (PMID 33194645, 2020). "DAB2, MMP14, and SPP1 were also consistently expressed in CD68+ microglia/macrophages in patient-derived breast cancer BrM (n = 4), while their expression was absent from the patient-matched blood." (PMID 31501884, 2020). "On comparing the number of immune cells expressing immune cell subtype-related proteins, we found that the expression of STAT6 (p = 0.005), FOXP3 (p = 0.001), CD8 (p = 0.012), CD68 (p = 0.011), and CD163 (p < 0.001) differed significantly according to the breast cancer molecular subtypes." (PMID 32580398, 2020). "Bone or brain metastatic status had higher CD68 level compared to non-mineral metastatic breast cancer cases." (PMID 31935914, 2020). "First, there are multiple studies illustrating the negative influence of CD68+ macrophages on overall survival of breast cancer patients." (PMID 33377644, 2020). "Analysis of the TCGA breast cancer database shows a highly significant correlation between CD163 or CD68 and SIGLEC9 but not with the epithelial markers, EPCAM or KRT8." (PMID 33149188, 2020). "The amount of CD68+ macrophages in tumor stroma in different cohorts of patients (Chinese, Finnish, Swedish, Korean, UK, and USA cohorts) was an independent prognostic factor for reduced OS, DFS, and RFS of patients with breast cancer." (PMID 33194645, 2020). "Niet al.38 suggested that the CD68 positive macrophage is one of the tumor-infiltrating macrophages in non-metastatic breast cancer." (PMID 32695310, 2019). "Our study also confirmed the first time that the prognostic significance of combined high expression of CD47 and CD68 not only in breast cancer in general, but also in hormone receptor-negative breast cancer in particular." (PMID 31528120, 2019). "Our study showed for the first time that CD47highCD68high represented an even better independent predictor for poor prognosis compared to the expression of CD47 or CD68 alone in breast cancer patients, especially in patients lacking of hormone receptor." (PMID 31528120, 2019). "The exact role of CD47 and CD68 in breast cancer, especially in hormone receptor-negative breast cancer, still needs to be evaluated in follow-up mechanistic investigations." (PMID 31528120, 2019). "The aims of this study were to objectively determine the in situ expression and significance of TAM biomarkers (CD68, CD163, and MMP-9) in breast cancer and to identify subclasses of patients who could benefit from TAM-targeting therapies." (PMID 30558648, 2018). "In conclusion, the retrospective study including 98 breast cancer patients treated with anti-Her-2 therapy revealed that tumor TILs as well as its FOXP3+, CD68+ phenotypes in stromal site, and expression of FOXP3 in cancer cells were significantly associated with OS." (PMID 28029650, 2017).
breast carcinoma (continued). "In this retrospective analysis including 98 breast cancer patients treated with anti-Her-2 therapy, we studied potential relationship between TILs infiltration, count of FOXP3+ Tregs, CD68+ Mφ and IL-17+ Th17 in both intratumoral and stromal site with patients’ survival." (PMID 28029650, 2017). "Clinically, breast cancer patients possess sCLU expression only in mature CD68+ macrophages but not in immature CD33+ immunosuppressive myeloid cells infiltrating the tumors." (PMID 27405665, 2016). "Interestingly, we observed a different distribution of CD68+ cells within TNBC and HER2+ breast cancer samples." (PMID 27713152, 2016). "However, other research reported that CD68+ TAMs in tumor stroma was an independent prognostic factor for poor OS and TTR in breast cancer, cholangiocarcinoma and Hodgkin lymphoma." (PMID 26938527, 2016). "Our observation of selective expression of sCLU in infiltrating CD68+ macrophages but not in CD33+ immature myeloid cells within breast cancer tissues is an important new finding that explains the immune-restorative capacity of certain anti-cancer drugs." (PMID 27405665, 2016). "By comparison of breast cancer cell lines BJMC338 and BJMC3879 having low and high metastatic potential, respectively, more aggressive tumors were found to have an increased infiltration of CD68+ macrophages, higher expression of VEGF-C and a higher LVD." (PMID 24634660, 2014). "Taken together, infiltration of CD163+ and CD68+ macrophages into TS, but not TN, is of clinical relevance for breast cancer patients and highlights the importance of analyzing the localization rather than merely the presence of TAMs as a prognostic marker." (PMID 22824040, 2012). "Here we show that infiltration of CD163+ and CD68+ macrophages into TS, but not TN, is of clinical relevance for breast cancer patients." (PMID 22824040, 2012). "Additionally, mIHC analysis of the breast cancer tissue microarray confirmed that CD8+ T cell, CD68+ (M0-like) macrophages, and CD68+CD163- (M1-like) macrophages infiltration levels were significantly higher in the LMF_index low group compared to the LMF_index high group." (PMID 40612672, 2025). "Also, THP-1 cells encountered breast cancer MDA-MB 231 cells those were pretreated with cisplatin and/or Oligo-Fucoidan expressed the higher mRNA levels of M0 (F4/80) and M1 (CD68 and CD86) marker." (PMID 32059469, 2020). "However, in contrast to breast cancer, CD68 was not frequently used as TAM marker to evaluate TAM levels." (PMID 33194645, 2020). "Moreover, Pearson's correlation analysis revealed that there was a significant negative correlation between the expression of CD68 and ER in the breast cancer (r=-0.75, P<0.001)." (PMID 31853223, 2019). "Combined detection of CD47 and CD68 may provide guidance for the prognosis of breast cancer, especially hormone receptor-negative breast cancer." (PMID 31528120, 2019). "Moreover, the prognostic significance of combined high expression of CD47 and CD68 not only in breast cancer in general, but also in hormone receptor-negative breast cancer in particular." (PMID 31528120, 2019). "Several studies reported that HER2+ breast cancer has more TAM infiltration (CD68-positive 10, 16; CD163-positive 9, 14, 16), while the majority of the included studies failed to reveal a significant relationship between HER2 expression and TAMs in breast cancer." (PMID 31528210, 2019). "In a hypothesis-generating study using human breast carcinoma treated with or without neoadjuvant chemotherapy, CD68 was found to play a role in the immune microenvironment of breast cancer." (PMID 29573739, 2018). "To determine whether macrophages cells do not contaminate the isolated cells prepared from breast cancer tissues, we used immunofluorescence to investigate the expression of various macrophage surface markers including F4/80, CD68 and CD163." (PMID 28178651, 2017).
breast carcinoma (continued). "To further validate that the macrophoages/TNFα could activate YAP and HK2 in vivo, we evaluated the relevance of CD68+ (highly expressed in blood monocytes and tissue macrophages) staining with YAP or HK2 staining in human breast cancer samples via immunohistochemical staining." (PMID 28945218, 2017). "We demonstrated that the CD169+ cell density and the CD169+/CD68+ macrophage ratio in the RLNs of breast cancer patients correlated with early clinical stage and no LN metastasis as well as with an increased density of CD8+ lymphocytes in cases with a Ki-67 index of >40%." (PMID 27861544, 2016). "Despite this evidence for inflammation providing a link between obesity and poor PCa outcomes, it has been suggested that there may not be a relationship between the number of CD68 macrophages and BMI among breast cancer patients." (PMID 27487262, 2016). "For this purpose the number of CD169+ cells and their ratio relative to total macrophages (CD68+) in regional LNs (RLNs), as well as the number of CD8+ CTLs in tumor tissues, were investigated using immunohistochemistry of paraffin-embedded tissue samples from 146 patients with breast cancer." (PMID 27861544, 2016). "Likewise, our group previously reported that tumors with MMP-11 expression by MICs showed a high cell immune ratio ((CD68+) macrophages/(CD3+) T cells + (CD20+) B cells) at the invasive front, an upregulation of inflammatory-related genes, and a poor prognosis in breast carcinomas." (PMID 33669393, 2021). "In the present comprehensive meta-analysis, we report that both CD68- and CD163-positive macrophages are significantly associated with poor prognosis, advanced histological grade, high Ki67 expression and negative hormonal receptor expression in early stage breast cancer." (PMID 31528210, 2019). "Our study showed for the first time that combined high expression of CD47 and CD68 represented an even better independent predictor for poor prognosis compared to the expression of CD47 or CD68 alone, and could be a novel prognostic factor for breast cancer patients." (PMID 31528120, 2019). "Similar to findings in this study, CD68+ TAMs did not significantly correlate with overall survival and recurrence-free survival (RFS) in multivariate analysis in basal-like breast cancer (BLBC) and triple-negative cancer of the breast." (PMID 37397243, 2023). "We found that the existence of CD68+ cells in TLSs was an independent prognostic factor in recurrent breast cancer, and PFS was significantly improved in patients with CD68+ cells in TLSs than in those without (HR: 0.411, 95% CI: 0.180–0.940, p = 0.035)." (PMID 38133211, 2023). "In the breast cancer tissue itself, 65% of dendritic cells, no CD45 positive cells, 20% of CD11b positive cells, and 10% of CD68 positive cells were found." (PMID 33921688, 2021). "In the breast cancer tissue itself, 45% of dendritic cells, no CD45 positive cells, 10% of CD11b positive cells, and no CD68 positive cells were found (for a summary of the results, and for a representation)." (PMID 33921688, 2021). "CD68 and CD163 have been broadly used to show that high TAM density correlates with a worse clinical outcome in breast cancer but do not predict their functional phenotype." (PMID 33968034, 2021). "Overall, our data indicated that stabilin-1 is expressed in human breast cancer with prevalent localization on TAM, and marks distinct subpopulation of cells in the tumor stroma with decreased or absent expression of CD68." (PMID 27105498, 2016). "In line with the findings from the TMA-based analysis, basal-like breast cancer had significantly higher gene expression levels of CD163 (P<.001) compared to luminal breast cancer, but also of CD68 (P<.05) (data not shown)." (PMID 22824040, 2012).